MNX1 (motor neuron and pancreas homeobox 1)
Description:
Transcription factor (By similarity). Recognizes and binds to the regulatory elements of target genes, such as visual system homeobox CHX10, negatively modulating transcription (By similarity). Plays a role in establishing motor neuron identity, in concert with LIM domain transcription factor LMO4 (By similarity). Involved in negatively modulating transcription of interneuron genes in motor neurons, acting, at least in part, by blocking regulatory sequence interactions of the ISL1-LHX3 complex (By similarity). Involved in pancreas development and function; may play a role in pancreatic cell fate specification (By similarity).
Synonyms: HLXB9; HB9; HOXHB9; SCRA1
Tractability: PROTAC: ubiquitination databases record sites on it.
Gene: Protein-coding gene on chromosome 7 (156,994,051 to 157,010,663, reverse strand). Ensembl gene ENSG00000130675.
Subcellular location: Nucleus
Subcellular location (Human Protein Atlas): Nucleoplasm; Cytosol; Nucleoli
Gene Ontology:
Molecular function: sequence-specific double-stranded DNA binding; DNA-binding transcription factor activity, RNA polymerase II-specific; DNA binding; DNA-binding transcription repressor activity, RNA polymerase II-specific
Biological process: central nervous system development; endocrine pancreas development; neuron projection morphogenesis; spinal cord motor neuron cell fate specification; negative regulation of transcription by RNA polymerase II; regulation of DNA-templated transcription
Cellular component: chromatin; nucleus
Genetic constraint (gnomAD): Loss-of-function variants: 3 observed, 12.23 expected, observed/expected ratio (o/e) 0.25, 90% interval 0.11 to 0.63. The synonymous counts are far from expectation, so gnomAD's model fits this gene poorly and the ratio says little. Missense variants: 542 observed, 473.33 expected, observed/expected ratio (o/e) 1.15, 90% interval 1.07 to 1.23. Synonymous variants: 299 observed, 236.73 expected, observed/expected ratio (o/e) 1.26, 90% interval 1.15 to 1.39.
Homologues: Orthologues: chimpanzee MNX1 (99% identical), macaque MNX1 (99% identical), dog MNX1 (93% identical), pig MNX1 (93% identical), rat Mnx1 (91% identical), mouse Mnx1 (90% identical), tropical clawed frog mnx1 (54% identical), zebrafish mnx1 (53% identical).
Diseases named in the same sentence as MNX1 in open-access papers:
MNX1 is named in the same sentence as 64 diseases in open-access papers, as found by Europe PMC text mining. Sharing a sentence is not in itself a finding about the gene and the disease. The quoted sentences say what the papers report.
Currarino syndrome (20 papers, 2008 to 2026). "Currarino syndrome is defined by a triad of sacral bone defects, anorectal malformations, and presacral masses and is often associated with mutations in the MNX1 gene located at 7q36.3." (PMID 41486773, 2026). "Heterozygous loss of function variants in MNX1 cause Currarino syndrome, a rare clinical condition that is characterised by presacral mass, sacral agenesis and an anorectal anomaly." (PMID 38932873, 2024). "Patient 5, a 38-year-old male with Currarino syndrome (germline MNX1 mutation), presented with low back pain and was found to have a pre-sacral mass as well as liver metastases." (PMID 39556303, 2024). "Mutations of the MNX1 gene have been found in patients with Currarino syndrome, and further molecular genetic correlations are being sought." (PMID 38893276, 2024). "Due to maternal history, a genetic analysis in the mother and amniocentesis were performed to search for MNX1 gene mutation; diagnosis of Currarino syndrome was made in both the mother and fetus." (PMID 36562956, 2023). "For example, variants in the MNX1 gene cause Currarino syndrome, which is characterized by sacral agenesis and imperforate anus." (PMID 34671974, 2022). "The MNX1 gene is associated with Currarino syndrome (OMIM 176450), an autosomal dominant syndrome characterized by association of partial sacral anomalies, a presacral mass, and anorectal malformations." (PMID 33584815, 2020). "Holoprosencephaly and Currarino triad have been reported in terminal deletions; these conditions are attributed to the loss of MNX1 and SHH." (PMID 26064708, 2015). "Currarino syndrome, characterized by the triad of partial sacral agenesis, presacral mass, and anorectal malformation, is caused by mutations in the MNX1 (HLXB9) gene in 50% of sporadic and 90% of familial cases with the classic phenotype." (PMID 23437000, 2013). "Additionally, an association with Currarino syndrome can be observed, an autosomal-dominant disorder caused by mutations in the motor neuron and pancreas homeobox 1 (MNX1) gene and characterized by presacral mass, sacral dysgenesis, anorectal anomalies." (PMID 34690926, 2021). "Indeed, mutations have been reported within the region encoding the polyalanine repeat in MNX1, and variation in the length is considered to be associated with the presence of Currarino syndrome." (PMID 32571425, 2020). "Moreover, MNX1 is associated with normal cells malignant transformation depending on its mutation causes congenital malformation---Currarino syndrome, suggesting that MNX1 may be a potential driver in tumorigenesis." (PMID 30012177, 2018). "MNX1 gene is involved in a congenital malformation, the Currarino syndrome (congenital malformation) and also previously reported in CD34+ cells, B cells and B lymphoid tissues." (PMID 22980038, 2012). "Interestingly, Currarino syndrome, characterized by the triad of hemisacrum, anorectal malformation and pre-sacral mass, is caused by mutations in the HLXB9 gene (also known as MNX1), which is known to have a role in pancreas and motor neuron development." (PMID 23437000, 2013). "Mutations in the MNX1/HLXB9 gene may cause neonatal diabetes and Currarino syndrome." (PMID 26859147, 2016). "Importantly, mice lacking Mnx1 do not mirror the caudal phenotype seen in human patients with Currarino syndrome." (PMID 23437000, 2013). "Although the expression of MNX1 is limited by haploinsufficiency in Currarino syndrome, the degree of transcriptional repression of the nonmutated allele may not be identical for every patient with a given mutation, and this could explain the large intra-mutational phenotypic variability." (PMID 32571425, 2020).
leukemia (12 papers, 2014 to 2026). A malignant (clonal) hematologic disorder, involving hematopoietic stem cells and characterized by the presence of primitive or atypical myeloid or lymphoid cells in the bone marrow and the blood. "In these instances, the MNX1 gene, implicated in leukemia onset, remains unaltered in its sequence but experiences a shift in its nuclear position, resulting in its activation." (PMID 38927657, 2024). "This warrants further investigation into the specific contributions of PBXIP1 and PBX4 to MNX1-driven leukemia and their potential as therapeutic targets." (PMID 41554854, 2026). "Together, these results suggest that while Pbx1 functions as an early target of MNX1 in preleukemic cells, Pbxip1 and Pbx4 act as secondary (indirect) targets whose altered expression arises with MNX1 leukemia progression." (PMID 41554854, 2026). "Like the MNX1-OE haemGx cells selected through serial replating, MNX1-OE mouse leukemia are also C-Kit+." (PMID 40932369, 2025). "We focused on MNX1-driven leukemia, representing the commonest genetic abnormality unique to the infant group." (PMID 40932369, 2025). "We harnessed the embryonic hematopoietic context provided by haemGx to attest its utility in modelling leukemias with developmental origins, specifically by recapitulating MNX1-r infant leukemia by proxy of MNX1 overexpression." (PMID 40932369, 2025). "This work provides support for a stage-specific role of MNX1 in leukaemia transformation of foetal cells, and further suggests a facilitating effect of the immature immune system of newborns in propagating the disease." (PMID 36622782, 2023). "During embryonic development, MNX1 uses upstream regulatory elements in a tissue-specific manner, and it is possible that in the context of leukaemia some of these distant regulatory elements are misused." (PMID 36622782, 2023). "We evaluated the nuclear location of the chromosomal region surrounding MNX1 in the leukemia K562 cell line by FISH, and assessed the transcriptional activity of genes mapping in same region (i.e., LMBR1, NOM1, MNX1, UBE3C, and PTPRN2) by qRT-PCR." (PMID 33652823, 2021). "In this study, we used FISH on 3D-preserved nuclei to investigate the nuclear positioning of MNX1 in the leukemia-derived cell line K562." (PMID 33652823, 2021). "Through a xenograft mouse model, we demonstrated that MNX1 is required for leukemia cell fitness." (PMID 40162972, 2025). "After having demonstrated that MNX1 can be activated by enhancer hijacking in AML, we investigated whether MNX1 plays a role in the maintenance of established leukemias." (PMID 40162972, 2025). "However, in leukemia patients, MNX1 is re-positioned towards the inner part of the leukemic cell nuclei, a compartment where genes are generally expressed." (PMID 33652823, 2021). "In vivo, transplantations of MNX1 overexpressing bone marrow cells did not cause leukaemia in the recipients, but resulted in an accumulation of MNX1-overexpressing cells in the megakaryocytic-erythrocyte fraction, but not in the granulocytic-monocyte nor in the mature lymphoid compartments." (PMID 36057683, 2022). "We further investigated the potential of MNX1-OE haemGx to reflect MNX1-r AML biology by performing serial replating of CFC assays, a classical in vitro assay of leukemia transformation." (PMID 40932369, 2025). "We modelled MNX1-r AML, a poorly characterized form of leukemia exclusive to the infant age group." (PMID 40932369, 2025). "MNX1-OE C-Kit+ cells co-expressed CD31, underpinning the endothelial signatures of MNX1-r leukemia." (PMID 40932369, 2025). "A recent paper using MNX1-OE has shown that MNX1 can initiate a transplantable leukemia in immunodeficient mice by targeting FL, but not BM, cells." (PMID 40932369, 2025).
acute myeloid leukemia (11 papers, 2014 to 2025). Acute myeloid leukemia (AML) is a group of neoplasms arising from precursor cells committed to the myeloid cell-line differentiation. "In addition, MNX1 is a causative oncogene in infant acute myeloid leukemias (AML)." (PMID 30012177, 2018). "Systematic discovery of enhancer hijacking in complex karyotype acute myeloid leukemia via the new tool Pyjacker identifies MNX1 activation, a novel leukemogenic event that can result from 7q deletion, among other events." (PMID 40162972, 2025). "In follow-up study, MNX1 was found to be abnormally expressed in several cancer types, including prostate cancer, hepatocellular carcinoma and acute myeloid leukemia." (PMID 32850410, 2020). "HaemGx with MNX1 overexpression recapitulate MNX1-r acute myeloid leukemia patient signatures." (PMID 40932369, 2025).
bladder cancer (8 papers, 2018 to 2025). "Herein, we show that MNX1 is obviously upregulated in bladder cancer cells and is associated with poorer prognosis." (PMID 30012177, 2018). "The mRNA and protein expression of MNX1 were markedly upregulated in bladder cancer cell lines as compared to primary normal urethral epithelial cells." (PMID 37627900, 2023). "To evaluate the relationship between MNX1 expression and the clinicopathological features of bladder cancer, we analyzed 167 human bladder cancer tissue samples by IHC." (PMID 30012177, 2018). "In vitro function of MNX1 (Motor neuron and pancreas homeobox 1) in bladder cancer cell was evaluated using MTT assay, colony formation assay, and bromodeoxyuridine incorporation assay." (PMID 30012177, 2018). "To investigate the spectrum of MNX1 expression in bladder cancer, we first analyzed MNX1 expression in publicly available human bladder cancer datasets from The Cancer Genome Atlas (TCGA) and Gene Expression Omnibus (GEO)." (PMID 30012177, 2018). "In summary, our study reveals that MNX1 upregulation plays an important role in bladder cancer progression and that it is a critical cell cycle promoter that upregulates CCNE1 and CCNE2 directly." (PMID 30012177, 2018). "Abnormal MNX1 upregulation in bladder cancer cell lines and 167 human tissue specimens; high MNX1 expression levels correlated significantly with shorter 5-year overall and relapse-free survival in the bladder cancer patients." (PMID 30012177, 2018). "Our data reveal that ectopic expression of MNX1 promoted the formation of subcutaneous tumors in vivo, while silencing MNX1 inhibited it, which indicates MNX1 is an important factor in bladder cancer cell tumorigenicity." (PMID 30012177, 2018). "MNX1 mRNA levels were obviously upregulated in bladder cancer samples compared with normal bladder tissues." (PMID 30012177, 2018). "MNX1 overexpression markedly promoted bladder cancer cell proliferation and tumorigenicity both in vitro and in vivo, whereas MNX1 silencing inhibited it." (PMID 30012177, 2018). "To further explore the effects of MNX1 in bladder cancer tumorigenesis in vivo, we established MNX1 stable overexpression and knockdown in T24 cells." (PMID 30012177, 2018). "Western blotting and real-time PCR showed that MNX1 mRNA and protein expression, respectively, were markedly upregulated in all bladder cancer cell lines compared to primary normal urethral epithelial cells." (PMID 30012177, 2018). "To further investigate the effect of MNX1 in bladder cancer progression, we first established MNX1 stable overexpression and knockdown in T24 and 5637 cell lines." (PMID 30012177, 2018). "Herein, we found that MNX1 was robustly upregulated in bladder cancer, and established a vital role for MNX1 as a tumor-promoting factor of bladder cancer proliferation and tumorigenicity." (PMID 30012177, 2018). "The potential correlation between the expression status of MNX1 and clinical pathologic parameters of patients with bladder cancer was further analyzed." (PMID 30012177, 2018). "As MNX1 is involved in the cell cycle regulation of bladder cancer cells, we examined the expression of cell cycle regulators." (PMID 30012177, 2018). "The subsequent colony formation assay showed that MNX1 promoted bladder cancer cell colony numbers significantly, while silencing MNX1 had the opposite effects, and the colony numbers were counted and shown in histogram." (PMID 30012177, 2018). "The tetrazolium (MTT) assay showed that MNX1 upregulation increased the proliferation rate of bladder cancer cells; MNX1 depletion reduced it." (PMID 30012177, 2018). "Our results reveal a novel mechanism for the oncogenic role of MNX1 in bladder cancer and suggest MNX1 as a new biomarker and potential therapeutic target." (PMID 30012177, 2018). "In addition, MNX1 expression was also significantly higher in bladder cancer tissues than in paired adjacent normal tissues." (PMID 37627900, 2023).
bladder cancer (continued). "High MNX1 expression was significantly correlated with a shorter 5-year overall and relapse-free survival, thus suggesting that MNX1 expression is related to a poor bladder cancer prognosis." (PMID 37627900, 2023). "In addition, it has been demonstrated that MNX1 induces bladder cancer proliferation and tumorigenicity by targeting promoters to upregulate CCNE1 and CCNE2 expression." (PMID 36316768, 2022). "Furthermore, recent studies confirmed that MNX1 played oncogenic roles in colorectal cancer, breast cancer, and bladder cancer." (PMID 32850410, 2020). "Our findings suggest that MNX1 is a potential therapeutic target against bladder cancer." (PMID 30012177, 2018). "Strikingly, IHC could detect MNX1 at all T classifications in the bladder cancer specimens and it correlated with poor outcome." (PMID 30012177, 2018). "Strikingly, we found that MNX1 overexpression enhanced bladder cancer cell proliferation." (PMID 30012177, 2018). "To further evaluate whether this MNX1-induced promotion of cell proliferation was due to the inhibition of cell cycle arrest, we examined the effect of MNX1 on cell cycle of bladder cancer cells." (PMID 30012177, 2018). "Furthermore, MNX1 overexpression accelerated bladder cancer cell proliferation and tumorigenicity both in vitro and in vivo, whereas MNX1 downregulation arrested it." (PMID 30012177, 2018). "In addition, univariate Cox regression analysis indicated that the MNX1 expression and T stage status were each recognized as independent prognostic factors for the 5-year overall survival in bladder cancer." (PMID 30012177, 2018). "We then detected MNX1 expression in bladder cancer cell lines and tissues." (PMID 30012177, 2018). "Furthermore, we found that MNX1 can accelerate G1–S transition in the bladder cancer cell cycle by transcriptionally upregulating CCNE1 and CCNE2 expression." (PMID 30012177, 2018). "Taken together, these results show that MNX1 is upregulated in bladder cancer cell lines and tissues, and that it might lead to poor clinical outcome." (PMID 30012177, 2018). "We reported that MNX1 is responsible for sustaining bladder cancer cell proliferation." (PMID 30012177, 2018). "Therefore, our results suggest that MNX1 may be an oncogene and might represent a novel prognostic biomarker in bladder cancer." (PMID 30012177, 2018). "However, the clinical importance and biological role of MNX1 in bladder cancer remain largely unknown." (PMID 30012177, 2018). "Similarly, IHC indicated that MNX1 was greatly overexpressed in bladder cancer samples." (PMID 30012177, 2018). "However, more MNX1 mechanisms and functions in bladder cancer require further exploration." (PMID 30012177, 2018). "As expected, luciferase reporter assays revealed that MNX1 overexpression activated the luciferase activity of CCNE1 and CCNE2 promoters in the bladder cancer cells, whereas MNX1 downregulation attenuated it." (PMID 30012177, 2018). "Herein, we investigated that MNX1 upregulates CCNE1 and CCNE2 expression to induce proliferation and tumorigenicity in bladder cancer by targeting their promoters." (PMID 30012177, 2018). "In addition, MNX1 transcriptionally upregulated CCNE1 and CCNE2 by directly bounding to their promoters, which promoted G1–S transition in the bladder cancer cells." (PMID 30012177, 2018). "Consistently, MNX1 expression was significantly higher in eight human bladder cancer tissues than in the paired adjacent non-tumor tissues." (PMID 30012177, 2018).